TNF (tumor necrosis factor)
Diseases named in the same sentence as TNF in open-access papers (continued):
Sharing a sentence is not in itself a finding about the gene and the disease.
type 2 diabetes (continued). "It has beneficial antidiabetic effects on type 2 diabetic rats by affecting the AMPK-mediated signaling pathway in the pancreas by inhibiting the production of TNF-α, IL-6, caspase-3, IL-1, and apoptosis, and restoring pancreatic beta cells." (PMID 37943820, 2023). "Compared to healthy, levels of TNF-α were decreased in type 1 diabetes and increased in type 2 diabetes, while colonic transit time was increased (all p < 0.05)." (PMID 37189645, 2023). "In obese type 2 diabetes patients, the TNF-α plasma level is related to the amount of visceral fat and is not instantly affected in poorly controlled diabetic patients by acute lowering of blood glucose level." (PMID 37215099, 2023). "In another study, besides CRP, TNF was also found to be an independent predictor of diabetic kidney disease in type 2 diabetes patients." (PMID 37762893, 2023). "In type 2 diabetes, TNF-α can mediate its biological effect in adipose tissues through its receptor, TNFR1." (PMID 37215099, 2023). "Western blot indicated that the levels of TNF were enhanced in gingivitis of type 2 diabetes compared with normal tissues (P < .01)." (PMID 37986309, 2023). "In type 2 diabetic patients, dendritic cells have been shown to accumulate in adipose tissue and promote the production of pro-inflammatory cytokines, such as IL-6 and TNF-α, by T cells." (PMID 38094119, 2023). "C. papaya reinstated the levels of adipocytokines, antioxidant enzymes and mRNA levels of mTOR, TNF-α, IL-1β, IL-6 and IKKβ in the adipose tissues of type 2 diabetic rats." (PMID 36826001, 2023). "In the remaining samples (healthy: 20; type 1 diabetes: 52; type 2 diabetes: 86), inflammatory cytokines were successfully measured in 99% (IL-6, TNF-α) and 100% (IL-8, IL-10, IFN-γ) of cases." (PMID 37189645, 2023). "Previously, treatment with aqueous extract from Ajwa seed was seen to significantly decline brain COX-2, IL-6, and TNF-α levels in type 2 diabetic-induced rats." (PMID 36840284, 2023). "Subjects with type 2 diabetes had significantly increased plasma concentrations of TNF, total ceramides, and C18:0, C20:0 and C24:1 ceramide species." (PMID 37762318, 2023). "The increased level of TNF‐α induces insulin resistance in adipocytes and peripheral tissues by impairing the insulin signaling, which leads to the development of type 2 diabetes." (PMID 36655073, 2023). "The landmark studies correlating inflammation with diabetes were conducted in early 90’s by Hotamisligil group, who reported the critical role of TNF-α in obesity and Type II diabetes." (PMID 36804872, 2023). "This study found that CK treatment significantly reduced inflammatory factors, including TNF-α, IL-6, and IL-1β, in the liver injury model of type 2 diabetes rats." (PMID 37251340, 2023). "Probiotics showed the potential to reduce the serum concentration of IL-6, TNF-α, and hs-CRP, which are the major risk factors for inflammation-dependent metabolic diseases like type-2 diabetes." (PMID 36211513, 2022). "The metabolic stress observed in type 2 diabetes can induce the pro-inflammatory cytokines, tumor necrosis factor-α (TNF-α) and interleukin-6 (IL-6), activating a series of complex processes leading to apoptotic death of pancreatic β cells." (PMID 35054822, 2022). "Type II diabetes has been reported to have various aberrancies such as an impaired differential potential and secretion of multiple proinflammatory cytokines such as TNF-α and IFN-γ." (PMID 35572555, 2022). "Type 2 diabetes (T2D) mellitus is a chronic inflammatory disease characterized with high secretion of tumor necrosis factor (TNF)-α, but the regulatory pathway of TNF-α production in T2D has not been fully elucidated." (PMID 35712257, 2022).
type 2 diabetes (continued). "In our review of the relevant literature, we identified one other study reporting a significantly higher level of TNF-α based on the MAC status of eighty patients who had both type 2 diabetes and stage 2–4 chronic kidney disease." (PMID 36143268, 2022). "We found significant positive correlations between TNFα, sICAM-1 and PGRN in patients with type 2 diabetes and peripheral neuropathy, which also underlines the impact of PGRN on the inflammatory processes." (PMID 35453521, 2022). "According to previous studies, the serum concentrations of TNF-α levels were increased in the type 2 diabetes group but were highest in the type 2 DN group." (PMID 36363561, 2022). "Positive CD4+T cell response was defined as the presence of TNFα and/or IFNγ production following peptide stimulation and similar responses were observed between participants with type 2 diabetes and HCs." (PMID 36304475, 2022). "A recent study, described that almost 20 circulating cytokines such as TNFα, IL-1a, IL-1b, GM-CSF, IL-10, IL-12, etc., are elevated in plasma of type 2 diabetic patients." (PMID 34202017, 2021). "This study aimed to investigate the effects of 4 weeks of HFD consumption with a low dose of STZ, 12 weeks of AET (5 days/week) and RET (3 days/week), and 4 weeks of de-training on leptin, TNF-α and other metabolic parameters in type 2 diabetic rats." (PMID 34039404, 2021). "Among them, TNFα and IL-1b are two cytokines known to be upregulated in type 2 diabetic patients, which have demonstrated in vitro and in vivo animal models the ability to reduce the functional expression of the cardiac repolarizing current Ito." (PMID 34202017, 2021). "TNF‐α has been demonstrated to promote arterial calcification in type II diabetes (T2DM) mouse model through enhancing Msx2‐Wnt signalling." (PMID 33369201, 2021). "This study confirms a significant increase (p < 0.05) in the mRNA expression of TNF-α and IL- 6 in the adipose tissue of type-2 diabetic rats." (PMID 33917607, 2021). "The underlying mechanism may be related to inflammatory mediators including IL-6, IL-1α, and TNF-α, which not only promote epithelial–mesenchymal transition through activation of the Janus kinase/signal transducer and activator of trans-ions pathway but also increase the risk of type 2 diabetes." (PMID 34956904, 2021). "Other factors such as steroid intake, anti-TNF medication, type 2 diabetes, and transplantation history were only significant in the phase I cohort, reflecting underlying heterogeneity among cohorts." (PMID 33841421, 2021). "Here, we demonstrated the role of two of them, TNFα and IL-1b, in the cardiac electrical remodeling of type 2 diabetes." (PMID 34202017, 2021). "Two studies, one of which consisted of over 1200 adults with newly diagnosed type 2 diabetes, measured TNF-α concentrations." (PMID 33064180, 2021). "A series of studies have demonstrated that a chronic and low-grade inflammation, characterized by the elevated pro-inflammatory cytokines such as TNF-α and IL-6, exists in obese and type 2 diabetic patients." (PMID 34621265, 2021). "This study investigated the association of selected salivary inflammatory biomarkers (Interleukin 6 [IL-6], C-reactive protein [CRP], and Tumour necrosis factor α [TNF-α]) to glycated haemoglobin (HbA1C) in type 2 diabetics." (PMID 33676486, 2021). "Our trial showed that 3 g of cinnamon supplementation for 8 weeks had no beneficial impacts on plasma levels of NF-kB, SIRT1 and systemic inflammation factors including hs-CRP, IL-6 and TNF-α in type 2 diabetic patients." (PMID 31901246, 2020). "These modules consist of cAMP signaling pathway, serotonergic synapse, IL-17 signaling pathway, cholinergic synapse, TNF signaling pathway, type II diabetes mellitus and so on." (PMID 33390981, 2020). "We showed that type 2 diabetes in this model is associated with renal inflammation, as indicated by the increased protein expression of inflammatory markers MCP1, TNFα, TGFβ, and IL-18." (PMID 32218769, 2020).
type 2 diabetes (continued). "This study elucidated that cinnamon supplementation has no beneficial effects in reduction of NF-kB, SIRT1, hs-CRP, IL-6 and TNF-α levels in type 2 diabetes patients which have a considerable role in development of atherogenesis." (PMID 31901246, 2020). "The blood concentration of TNF-α has been reported to increase in dementia and type 2 diabetes, as well as with age15,16." (PMID 32601400, 2020). "Our purpose was to evaluate the effect of daily supplementation of three-gram cinnamon on plasma levels of NF-kB, SIRT, hs-CRP, IL-6 and TNF-α among type 2 diabetes patients." (PMID 31901246, 2020). "We also found that ouabain (100 nM) promoted the secretion of IL-6, IL-8, GM-CSF, and TNF-α from the skeletal muscle cells of healthy subjects, and the secretion of GM-CSF from cells of subjects with the type 2 diabetes." (PMID 33101052, 2020). "Our purpose was to evaluate the effect of cinnamon supplementation on NF-kB, SIRT1 and systemic inflammation factors (hs-CRP, IL-6 and TNF-α) levels among type 2 diabetes patients." (PMID 31901246, 2020). "ACEI were shown to inhibit LTA4 hydrolase (and consequently, LTB4 synthesis), to reduce monocyte chemoattractant protein-1 expression in macrophages and to decrease IL6 and tumor necrosis factor in normotensive type 2 diabetes individuals, among other effects." (PMID 32273829, 2020). "Consistent with this, gene set enrichment analysis revealed a strong correlation of genes upregulated in PBMCs from drug-naive patients with type 2 diabetes with a gene set that identifies TNF-α signaling via nuclear factor kappa B." (PMID 30867412, 2019). "Released TNF involves the immune system in response to stimulus (obesity or type 2 diabetes) and changes brain activity." (PMID 31275881, 2019). "Clinical and preclinical studies pointed out an increase in plasmatic level of TNFα, in type 2 diabetes, notably in women." (PMID 30792662, 2019). "This study purpose was to assess the vitamin D supplementation effectiveness on GLO1 and RAGE genes expression and also on AGES and TNF-α serum level in type 2 diabetic patients." (PMID 31673295, 2019). "Urinary Tf, IgG, NGAL, and TNF-α were found to be significantly related to the UACR in patients with type 2 diabetes (P < 0.001)." (PMID 31218128, 2019). "Safranal reduces inflammation of the pancreas and plasma and also decreases the oxidative stress of type 2 diabetes in plasma and pancreas by reducing TNF-α and IL-β levels." (PMID 32133067, 2019). "Compared to the normoalbuminuria group, a 90% increase in urinary TNF-α excretion was present in type 2 diabetic patients with microalbuminuria, which was further correlated with the UACR." (PMID 31218128, 2019). "Increased production of proinflammatory cytokines, such as IL‐6 and TNF‐α, plays an important role in the pathogenesis of type 2 diabetes and contributes to long‐term micro and macrovascular complications." (PMID 31183921, 2019). "Skeletal muscle atrophy usually occurs in type 2 diabetes and is controlled by the action of TNFα on the protein degradation pathway." (PMID 31828157, 2019). "Assessment of Tf, IgG, NGAL, and TNF-α in the diagnosis of early-stage diabetic nephropathy in patients with type 2 diabetes." (PMID 31218128, 2019). "Type 2 diabetes (T2DM) and its complications are associated with a systemic low-grade inflammation manifested by higher systemic levels of proinflammatory cytokines, such as IL-6, IL-1β, or TNFα." (PMID 30983877, 2019). "In type-2 diabetic patients, TNF-α was significantly decreased after the treatment with Brazilian green propolis, however IL-1β and IL-6 were significantly increased." (PMID 31717277, 2019). "The primary finding of this study was that urinary Tf, IgG, NGAL, and TNF-α levels, both individually and in combination, are valuable biomarkers for assessing early-stage DN in patients with type 2 diabetes." (PMID 31218128, 2019).
type 2 diabetes (continued). "Although only observational in nature, these studies demonstrate that in patients with type 2 diabetes and diabetic kidney disease, circulating levels of C-reactive protein, fibrinogen, interleukin-6, and tumor necrosis factor are significantly increased." (PMID 29910771, 2018). "It has been reported that plasma TNF-α concentrations in obese type 2 diabetics correlate with long chain plasma ceramides." (PMID 30474555, 2018). "IL-4, an anti-inflammatory cytokine, and TNF-α, a proinflammatory cytokine, levels shift in both type 1 and type 2 diabetes." (PMID 30345315, 2018). "ASE associated with exercise training potentiated the reduction of glycemia by decreasing TNF-α levels, increasing pAKT and adiponectin expressions in adipose tissue, and IR and pAMPK expressions in skeletal muscle of type 2 diabetic rats." (PMID 29920546, 2018). "Cross-sectional studies of C-reactive protein, interleukin-6, and tumor necrosis factor-α in type 2 diabetes." (PMID 29910771, 2018). "Longitudinal studies of C-reactive protein, interleukin-6, tumor necrosis factor-α, fibrinogen, and plasminogen activator inhibitor-1 in type 2 diabetes." (PMID 29910771, 2018). "The circulating markers of inflammation (e.g., TNF-α and IL-6) and acute-phase reactants (e.g., CRP) are considered strong predictors of the development of type 2 diabetes and the possible associated cardiovascular complications." (PMID 29755566, 2018). "TNF-α, IL6, MCP1 and IL1-β, were also significantly upregulated (p < 0.05) in PBMCs from patients with type 2 diabetes, implying an acquisition state of senescence-associated secretory phenotype." (PMID 30139387, 2018). "A study showed that consuming a low GI diet for 30 days reduced body fat and TNF-α in patients with type 2 diabetes when both high GI and low GI diets had similar energy density, dietary fiber, and macronutrient contents." (PMID 29414858, 2018). "Vitamin D can suppress TNF-α and IL-6 production by activated-monocytes in type 2 diabetic patients." (PMID 29684027, 2018). "The most significant predicted upstream regulators were rosiglitazone, which is used for the treatment of type 2 diabetes and the pro-inflammatory cytokine TNF-α." (PMID 28713378, 2017). "Given the potential benefit of inhibiting TNFα9 and NF-κB8 in the treatment of type 2 diabetes, the effect of NF-κB inhibiting sodium salicylate and TNFα inhibiting etanercept was assessed in the DIO/STZ and DIO mouse model." (PMID 28740254, 2017). "During the development of type 2 diabetes, there is an increased secretion of TNF-α from infiltrated macrophages in the adipose tissues, which induces the production of several inflammatory cytokines, including IL-1β." (PMID 28405188, 2017). "Further animal experiments showed that inhibition of LncRNA NONRATT021972 indeed alleviate neuropathic pain of type 2 diabetes via decreasing TNF-α." (PMID 28928602, 2017). "Chronic exposure of islets to the inflammatory cytokines interleukin-1 beta (IL-1β), tumor necrosis factor-alpha (TNF-α) and interferon-gamma (IFN-γ) is associated with β-cell destruction and decreased secretory parameters in both Type 1 and Type 2 Diabetes." (PMID 28893192, 2017). "Whilst women tended to show elevations in biomarkers related to an increased risk of type 2 diabetes (HOMA IR, leptin and TNF-α), men showed a marked increase in the cardiovascular disease risk biomarker CRP." (PMID 29190710, 2017). "Plasma levels of both TNF-α and IL-6 were significantly higher (p < 0.05) in patients with type 2 diabetes compared to control subjects." (PMID 27904654, 2016). "Studies which capture additional inflammatory markers, such as interleukins and TNF-α, are now needed in order to obtain a more precise estimation of their role in social inequalities in type 2 diabetes and other inflammation-related diseases." (PMID 27101929, 2016).
type 2 diabetes (continued). "Vinik described activation of inflammatory cytokines like IL-6 and TNFα in newly diagnosed type 2 diabetes and that the inflammatory change correlates with abnormalities in sympathovagal balance." (PMID 27992613, 2016). "Plasma levels of both TNF-α (p < 0.001) and IL-6 (p = 0.002) were significantly higher in patients with type 2 diabetes compared to control subjects." (PMID 27904654, 2016). "Resveratrol restored endothelial function in type 2 diabetes by inhibiting TNFα-induced activation of NAD(P)H oxidase and preserving eNOS phosphorilation." (PMID 27298812, 2016). "In line, reduced muscle PGC-1α expression in glucose intolerant and type 2 diabetic patients significantly correlates with elevated IL-6 and TNFα." (PMID 27833743, 2016). "This is probably due to increased levels of inflammatory cytokines TNFα and IL-1α in Type 2 diabetes." (PMID 27649540, 2016). "This is in accordance with many studies which revealed the role of TNF-α in the induction of IR and type 2 diabetes." (PMID 25785277, 2015). "This review reported a statistically significant improvement in CRP and TNF-α serum levels after periodontal therapy in people with a number of comorbidities but not limited to type 2 diabetes." (PMID 26010492, 2015). "In contrast, other studies have reported higher GCF levels of TNF-α and IL-7 in patients with type 2 diabetes than in systemically healthy individuals." (PMID 26211001, 2015). "The overall findings indicate that leakage of the BRB and reduction of OBF in HF-STZ induced type 2 diabetic rat model are associated with hyperglycemia and the accumulations of free radicals, AGEs-RAGE, TNF-α, and VEGF levels in the retinal tissues." (PMID 25950001, 2015). "Our study demonstrates that PGRN concentrations and other inflammatory markers, such as TNF-α and IL-6, are markedly elevated in sera of type 2 diabetic patients with microangiopathy." (PMID 26106251, 2015). "In postmenopausal women with type-2 diabetes Zinc supplementation increases TNF-α gene expression, suggesting a close interaction between Zinc homeostasis, oxidative stress and inflammation." (PMID 26381880, 2015). "Hyperglycemia due to type 2 diabetes induces higher levels of some inflammatory cytokines such as TNF-α." (PMID 26693410, 2015). "The main finding of the review was that hs-CRP and TNF-α were statistically significantly lowered by PT in people with type 2 diabetes when compared to controls." (PMID 26010492, 2015). "We have previously demonstrated that TNFα is increased in rat retina with type 1 and type 2 diabetes." (PMID 25874611, 2015). "This is in agreement with previous results determining IL-1β in this model, although increased serum levels of TNF-α have been detected in high fat fed/streptozotocin-induced type 2 diabetic rats." (PMID 25518980, 2014). "A growing number of studies have confirmed that many types of inflammatory factors can predict the occurrence of type 2 diabetes, such as TNF-α and IL-6." (PMID 24633252, 2014). "The inflammatory cytokines tumor necrosis factor-alpha (TNF-α) and interleukin-1β (IL-1β) are implicated in both type 1 and type 2 diabetes." (PMID 24466329, 2014). "Markers of chronic low-grade inflammation, such as tumor necrosis factor-α (TNF-α), Interleukin-6 (IL-6), and high sensitive- C-reactive protein (hs-CRP) have been shown to predict the risk of developing type 2 diabetes and cardiovascular disease." (PMID 24495354, 2014). "It is likely that oxidative stress is associated in type 2 diabetic patients with a systemic inflammatory status characterized by increased levels of cytokines as IL6 and TNF-α." (PMID 23383177, 2013). "Our results first showed that the expression of inflammatory genes in duodenal tissues of obese men with type 2 diabetes is relatively low, particularly in the case of IL-6 and TNF-α." (PMID 23855973, 2013).